OR51G2 (olfactory receptor family 51 subfamily G member 2)
Description:
Odorant receptor.
Synonyms: OR11-28
Tractability: Antibody: UniProt places it where antibodies can reach, with medium confidence; UniProt predicts a signal peptide or a membrane-spanning region; its Gene Ontology location is reachable by antibodies, with medium confidence.
Gene: Protein-coding gene on chromosome 11 (4,912,588 to 4,919,350, reverse strand). Ensembl gene ENSG00000176893.
Subcellular location: Cell membrane
Pathways (Reactome):
Sensory Perception: Expression and translocation of olfactory receptors
Gene Ontology:
Molecular function: olfactory receptor activity; G protein-coupled receptor activity; signaling receptor activity
Biological process: cellular response to lipid; detection of chemical stimulus involved in sensory perception of smell; G protein-coupled receptor signaling pathway; system process
Cellular component: plasma membrane; membrane
Genetic constraint (gnomAD): Loss-of-function variants: 14 observed, 13.79 expected, observed/expected ratio (o/e) 1.01, 90% interval 0.67 to 1.58. The upper end of that interval is the gene's LOEUF score, 1.58, which puts it in group 6 of 6, group 1 being the genes least tolerant of losing a copy. Missense variants: 474 observed, 414.94 expected, observed/expected ratio (o/e) 1.14, 90% interval 1.06 to 1.23. Synonymous variants: 178 observed, 159.57 expected, observed/expected ratio (o/e) 1.12, 90% interval 0.99 to 1.26.
Homologues: Orthologues: macaque OR51G2 (94% identical), mouse Or51g2 (91% identical), rat Or51g2 (91% identical), rabbit OR51G2 (89% identical), dog OR51G2 (87% identical), pig OR51G2 (84% identical), tropical clawed frog or51ao1 (52% identical). Paralogues in human: OR51G1 (63% identical), OR51A4 (59% identical), OR51A2 (58% identical), OR51L1 (58% identical), OR51A7 (57% identical), OR51I2 (56% identical), OR51F2 (54% identical), OR51Q1 (54% identical), OR51B5 (53% identical), OR51C1 (53% identical), OR51E2 (53% identical), OR52K1 (52% identical), and 39 more.